EGFR (epidermal growth factor receptor)
Diseases named in the same sentence as EGFR in open-access papers (continued):
Sharing a sentence is not in itself a finding about the gene and the disease.
cancer (continued). "Ongoing study on the mechanisms of cancer invasiveness and cellular signaling will further advance our knowledge on how extracellular matrix and cellular factors such as versican and EGFR signaling impact patient outcomes and can be modulated in response to treatment." (PMID 22096483, 2011). "Epidermal growth factor receptor (EGFR) is an important target in cancer research." (PMID 21738572, 2011). "Both PTGS2 (COX-2) and EGFR pathways are activated in many human cancers." (PMID 24213116, 2011). "Our mechanistic study on EGFR related signaling demonstrates that chemotherapeutic drugs can have varying effects on signaling that may either positively or negatively impact cancer cell survival through mechanisms that influence apoptosis." (PMID 22096483, 2011). "In addition, EGFR-driven cell signaling contributes to the disease progression and cancer malignancy." (PMID 21858220, 2011). "It has also been reported that inhibition of EGFR may lead to apoptosis in certain cancer cell lines." (PMID 21943352, 2011). "In our study we concentrated on the expression of phosphorylated, active EGFR protein as the assessment of active protein (rather than total protein) or gene amplification status seems to be more valuable in terms of patient selection for anti-EGFR cancer therapy and their response to treatment." (PMID 21407808, 2011). "For those cancers without EGFR mutations, it has been shown that the expression levels of EGFR do not predict the success of these drugs and the response rate to these inhibitors remains poor." (PMID 21908901, 2011). "It has been recently described that derailed endocytosis is an emerging feature of cancer and receptor down-regulation induced by anti-EGFR MAbs was described as an important mechanisms responsible for growth factor receptors inactivation and termination of EGFR cascade signaling." (PMID 22185378, 2011). "Atypical expression or activity of EGFR is present in numerous kinds of cancer." (PMID 21304974, 2011). "There are presently two main classes of EGFR inhibitors that can be used in cancer therapy." (PMID 21811593, 2011). "Since we have demonstrated the existence of apoptotic potential due to ROS stress in EGFR-addicted cancer cells, we further postulate that the easement of ROS stress may desensitize the cancer cells to the targeted treatment." (PMID 22194952, 2011). "In this study, we employed wtEGFR-expressing and gefitinib-sensitive A431 epidermoid cell line and its gefitinib-resistant derivative, A431/GR to address whether BCRP/ABCG2 plays a role in determining EGFR-TKI sensitivity in wtEGFR-expressing cancer cells." (PMID 21731744, 2011). "SN38-resistant cancer cells might be more dependent on EGFR signalling pathways for survival, and therefore may become more sensitive to EGFR inhibitors." (PMID 21997136, 2011). "We believe that targeted-therapies have the potential to transform advanced cancer into a long-term controlled chronic disease, and EGFR-targeting may represent a suitable scenario to show that this approach is feasible." (PMID 24212794, 2011). "For example, anti-EGFR (epidermal growth factor receptor) antibody-conjugated GNRs bind specifically to the surface of the malignant type cells with a much higher affinity due to the over expressed EGFR on the cytoplasmic membrane of the cancer cells." (PMID 24212654, 2011). "Since the GEP100 PH domain interacts with both Her2 and EGFR, targeting this domain may provide novel cancer therapeutics." (PMID 21966491, 2011). "However, observing down regulation of EGFR in this cancer, we conclude that the control on proliferation is lost." (PMID 21884569, 2011).
cancer (continued). "This might indicate that EGFR was not only involved in cancer genesis but also played an important role in cancer progression." (PMID 21385353, 2011). "However, autophagy was detected in EGFR-TKIs treated cancer cells that are relatively resistant to EGFR-TKIs, such as A549, NCI-H1299 and SK-MES-1 cells." (PMID 21655094, 2011). "Recent evidences suggest the anti-cancer effects of BA, anti-inflammatory and anti-viral activities via various signaling pathways such as epidermal growth factor receptor (EGFR), hedgehog, signal transducer and activator of transcription 3 (STAT3) and nuclear factor-kappa B (NF-κB)." (PMID 21731766, 2011). "However, treatment of cancer cells with various signaling pathway inhibitors revealed that CIP2A mRNA expression was sensitive to inhibition of EGFR activity as well as inhibition or activation of MEK-ERK pathway." (PMID 21445343, 2011). "Relationships between the presence /absence of various gene mutations and the efficacy of molecular targeted agents have been identified in various cancers; for example, the efficacy of anti-EGFR antibody was limited to colorectal cancer patients with wild-type KRAS expression in the tumor." (PMID 24212807, 2011). "The simulation well reproduced the experimental phenomena that acute inactivation of EGFR oncogene results in a rapid diminution of the cell proliferation/pro-survival effectors p-ERK and p-AKT, and subsequent engagement of the pro-apoptotic effector p-p38 in EGFR addicted cancer cells." (PMID 22194952, 2011). "Based on these results and the current state of the art on EGFR-targeted therapies, we discuss the need to evaluate new therapeutic approaches using anti-EGFR agents, which would have the potential of transforming advanced cancer into a long-term controlled chronic disease." (PMID 24212794, 2011). "Importantly, integrin and EGFR pathways are closely intertwined and orchestrate cancer growth and invasion." (PMID 22053213, 2011). "Notably, epidermal growth factor receptor (EGFR) is also up-regulated by IFN, and this up-regulation of EGFR is a crucial factor underlying the susceptibility of affected cancer cells to anti-EGFR antibody therapy." (PMID 21573021, 2011). "The combination of an EGFR inhibitor with irinotecan might be more important for anti-cancer therapy than that with 5-FU or OXA." (PMID 21997136, 2011). "Laboratory findings have shown that activation of EGFR signaling may lead to VEGF expression in cancer cells." (PMID 22091430, 2011). "The limited data that currently exists not only to anti-EGFR agents but also to chemotherapy in general in H and N cancers beckons further concerted efforts into additional molecular taxinometry in order to start to substratify patient populations for treatment individualization." (PMID 21274259, 2010). "Thus, this aptamer can in principle be used to deliver drugs or other cytotoxic cargo into cancer cells that express EGFR." (PMID 27713328, 2010). "As with EGFR somatic mutations, there is currently little evidence to speculate on the overall predictive nature of these aberrations in H and N cancers receiving anti-EGFR-based agents." (PMID 21274259, 2010). "We chose 100 nM (15 μg/ml) dose of cetuximab for additional studies because this is a receptor saturating concentration optimal to inhibit growth of EGFR-dependent cancer cells in culture and achieved at steady-state in the plasma of patients receiving cetuximab." (PMID 20856931, 2010). "Furthermore, Lapatinib has been shown to sensitize cancer cells to chemotherapeutic drugs by inhibiting the EGFR, P-glycoprotein (Pgp) and breast cancer resistance protein (BCRP)." (PMID 21187973, 2010). "EGFR+ cancers were significantly more frequent in ICCs than in ECCs or GBCs." (PMID 21087480, 2010). "EGFR plays an important role in proliferation in cancer research." (PMID 20509930, 2010). "Inhibiting the EGFR represents a form of targeted cancer therapy." (PMID 20478052, 2010).
cancer (continued). "Therefore, knowledge of the KRAS gene mutation status is essential before the decision is made to treat a cancer patient using EGFR-targeted Panitumumab and Cetuximab therapy." (PMID 21197450, 2010). "The EGFR/ErbB1 is a gene located on chromosome 7p12 and has emerged as a significant factor in the development and growth of many types of cancer, playing an important role in cancer-cell proliferation, angiogenesis and metastasis." (PMID 20664595, 2010). "The objective of this study was to determine whether the molecular mechanisms seen in NSCLC regarding EGFR mutations and gene copy number and correlation with TKI response extend to H and N cancer." (PMID 21274259, 2010). "Overexpression of EGFR and its family members have been found in the majority of human cancers." (PMID 20828404, 2010). "Although other EGFR inhibitors, such as small tyrosine kinase inhibitors (TKIs; gefitinib and erlotinib) are available for the treatment of other tumor types; only modest response rates of up to 11% as monotherapy have been obtained in H and N cancers." (PMID 21274259, 2010). "Future studies should also explore the combined use of usually employed generic questionnaires and dermatologic-oriented tools, like Skindex-29, in an attempt to better define the ultimate impact of EGFR therapeutic approaches involving a constantly increasing number of cancer patients." (PMID 20398332, 2010). "Expression of EGFR is significantly related to chemosensitivity in many cancers." (PMID 20064265, 2010). "These cancer stem cells might be less dependent on growth pathways, such as the EGFR pathway and might survive drug inhibition." (PMID 21165163, 2010). "Furthermore, it has been shown in some cancers that overexpression of EGFR correlates to poor outcome." (PMID 22069569, 2010). "A number of these resistance mechanisms have been identified in both preclinical and clinical studies and include activation of oncogenic signaling, HGF, VEGF, and PI3K/AKT activation, the latter of which plays a role in de novo resistance and sustenance of EGFR activation in a number of cancers." (PMID 20628489, 2010). "Thus, although EGFR plays important roles in tumorigenesis, cancer cells are genetically unstable and can elude the effect of EGFR-targeted therapy through several well-characterized and some not-yet-known resistance mechanisms." (PMID 21209911, 2010). "Affecting EGFR is of great benefit in the combat of cancer and possibly inhibiting kinases that phosphorylate EGFR may provide the means to control, at least in part, expression of the EGFR." (PMID 21152443, 2010). "Cancer inhibition through EGFR-TK is one of the mechanisms of these compounds." (PMID 20657425, 2010). "Accordingly, EGFR antagonists are used therapeutically to treat cancer." (PMID 27713341, 2010). "Inhibition of EGFR in cancer patients may provide therapeutic benefits through not only disconnecting EGFR to its own direct effectors but also interfering with GPCR signaling." (PMID 20074357, 2010). "Surgical resection, radiotherapy, radiochemotherapy, induction chemotherapy, radiobiotherapy (with anti epidermal-growth-factor receptor (EGFR) like cetuximab and other anti EGFR), are the therapeutic methods in locally advanced cases, the most frequent mode of presentation of H&N cancers." (PMID 20809978, 2010). "EGFR expression in NSCLC cancer has been reported to be common (ranges from 40-80%)." (PMID 20096104, 2010). "Cancer patients with EGFR overexpression often have a worse prognosis." (PMID 20828404, 2010). "Thus, our work establishes an important principle for the first time that 1, 9 PA, as a lead compound, can sensitize cancer cells to cetuximab-mediated anti-EGFR therapy." (PMID 21209911, 2010). "Overexpression of EGFR is observed in approximately 60% of patients with non-small cell lung cancer (NSCLC), which is the largest subset of lung cancer and the major cause of cancer death around the world." (PMID 20657425, 2010).
cancer (continued). "EGFR has also been shown to be highly expressed in numerous types of human cancers." (PMID 20540809, 2010). "All of them have been applied clinically to cancer therapy involving EGFR." (PMID 20657425, 2010). "Recent studies in non small cell lung cancer (NSCLC) have revealed that mutations in epidermal growth factor receptor (EGFR) occur in 15% of Caucasians and 30% of Asians with NSCLC, and the presence of specific EGFR mutations is predictive of response to therapy and cancer outcome." (PMID 20942962, 2010). "All of these results suggest a close correlation between Wnt and EGFR signal pathways in cancers." (PMID 20828404, 2010). "Although some reports show that EGFR might antagonize Wnt signaling during development in Drosophila, an increasing body of evidence indicates that Wnt and EGFR signaling crosstalk and transactivate one another in development and cancer." (PMID 20828404, 2010). "All of these studies indicate that EGFR and β-catenin may be cooperating in tumorigenesis and that β-catenin might be a convergent point between EGFR and Wnt signaling in cancer development." (PMID 20828404, 2010). "Recent randomized studies have demonstrated that the combination of radiation with the anti-EGFR monoclonal antibody cetuximab results in improvements of response and overall survival over radiation alone in patients with locally advanced H and N cancer." (PMID 21274259, 2010). "Blockade of EGFR results in inhibition of growth in several human carcinoma cell lines." (PMID 20828404, 2010). "As E-cadherin contacts suppress EGFR/ERK signalling in urothelial cells, the implication is that E-cadherin loss may directly contribute to the activation of RTKs frequently reported in carcinomas, including those of the bladder (and references therein)." (PMID 21049033, 2010). "Gefitinib is an EGFR tyrosine kinase inhibitor that acts by binding to the adenosine triphosphate (ATP)-binding site of the enzyme, employed in the treatment of certain types of carcinomas." (PMID 21124760, 2010). "Additionally, Harvey and colleagues demonstrated that sCAR-fusion proteins retargeted to urokinase-type plasminogen activator receptor (uPAR) and EGFR, improved the transduction of a number of carcinoma cell lines." (PMID 21994621, 2010). "According to our recent findings, cancer mutations in ABL and EGFR kinases, that display high oncogenic activity, may also induce the greater differential effect on thermodynamic stability of the inactive and active kinase forms." (PMID 19834613, 2009). "We hope that this special issue will stimulate interests and new researches in the development of anti-EGFR therapy in cancers, particularly the development of personalized medicine based on predictive biomarkers so that therapy can be tailored and optimized in every patient." (PMID 19750187, 2009). "Thus far, most studies have focused on evaluating EGFR in relation to cancer progression and targeted treatment." (PMID 19603096, 2009). "It was suggested that there is a need to use anti-EGFR as a novel anti-cancer therapy in bladder." (PMID 19243595, 2009). "It is likely knowledge of the relationship between differential expression and cellular localization of EGFR and its ligands in normal and neoplastic lesions and patient survival might be beneficial in developing potential targeted agents for cancer therapy." (PMID 19747398, 2009). "The approach of inhibiting IGF1R with a small molecule is validated by the numerous receptor tyrosine kinases (RTKs) that have been effectively targeted in the treatment of cancer, including Bcr-Abl (imatinib), EGFR (erlotinib, gefitinib) and EGFR/ErbB2 (lapatinib)." (PMID 19732452, 2009).
cancer (continued). "Signaling through EGFR (ErbB1) and its family members ErbB2 (Her2/Neu2) ErbB3 and ErbB4 regulates cellular processes such as survival, proliferation, differentiation and motility and ErbB receptors are important targets for new and existing anti-cancer drugs." (PMID 19662154, 2009). "Similar nuclear localization has been previously observed for Notch4 and epidermal growth factor receptor (EGFR) in cancers; however, their significance remains unknown currently." (PMID 20030805, 2009). "The crystal structures of EGFR-L858R, EGFR-T790M and ABL-T315I mutants have shown that these cancer-causing modifications could stabilize the active kinase form." (PMID 19714203, 2009). "Mutations involving alternate RAS isoforms are rare in these cancer types; conceivably, these might also confer resistance to anti-EGFR therapy." (PMID 19924296, 2009). "It is also possible that different ligands may have different roles within autocrine EGFR activation loop in different cancers." (PMID 19127259, 2009). "As already discussed, this pathway might provide alternative targets for the treatment of patients with cancer that has become resistant to the currently available EGFR inhibitors." (PMID 19416474, 2009). "Anti-EGFR monoclonal antibodies (MAbs) are important molecular-targeted drugs for cancer treatment." (PMID 19654571, 2009). "In contrast, EGFR staining in luminal A subtype carcinoma was weak and focal." (PMID 19442295, 2009). "In addition, in human cancer cells the EGFR autocrine pathway controls the production of several proangiogenic growth factors, including VEGF." (PMID 18522728, 2008). "Nevertheless, a comment could be addressed: in the trial of Zampino and co-workers, patients were enrolled if they had at least 20% cancer cells positive for EGFR, while in our trial only 1% of EGFR positivity was required as per standard practice." (PMID 18059397, 2008). "Furthermore, our findings suggest that TNK2 is potentially an attractive target for EGFR-dependent cancers or for cancers where the only available drugable receptor is the EGFR." (PMID 18435854, 2008). "The response rate to EGFR tyrosine kinase inhibitors (TKIs) may be poor and unpredictable in cancer patients with EGFR expression itself being an inadequate response indicator." (PMID 18682844, 2008). "Indeed, the EGFR pathway is involved in the proliferation of normal neural stem cells and cancer stem cells." (PMID 18492260, 2008). "However, there still remain a number of cancers characterized by EGFR overexpression that are refractory to these therapies." (PMID 21892266, 2008). "To test the antiproliferative effect of enzastaurin on cancer cell growth, we treated with different doses of enzastaurin several human cancer cell lines growing in soft agar with established differential sensitivity to EGFR inhibitors, including colon GEO, prostate PC3 and breast MDA-468 cells." (PMID 18665191, 2008). "When considering the overall data available it can be stated that the EGFR should be examined as a potential target for treatment in a significant minority of ovarium cancer patients and in particular for the 13% of patients with a cancer having high polysomy." (PMID 18182111, 2008). "As such, EGFR is considered to be a key therapeutic target for human cancers." (PMID 18302761, 2008). "The combination of everolimus with an EGFR inhibitor potentiates this effect, and it may resensitise resistant cancer cells to EGFR antagonists." (PMID 18319715, 2008). "However, to become an effective therapeutic target for other cancers that have elevated levels of EGFR activity, current approaches for inhibiting EGFR signaling will need to be refined." (PMID 21892266, 2008). "However, this therapeutic approach has limitations due to the constitutive and/or acquired resistance to EGFR inhibitors, which represents an important emerging problem in cancer treatment." (PMID 18665191, 2008).